FABP4 (fatty acid binding protein 4)
Diseases named in the same sentence as FABP4 in open-access papers (continued):
Sharing a sentence is not in itself a finding about the gene and the disease.
colon cancer (continued). "The influence of FABP4 on colon cancer metastasis was further confirmed in nude mouse model." (PMID 33088219, 2020). "In our experiment, bioinformatics analysis discovered that FABP4 was enriched in 11 pathways related to metabolism, including lipid metabolism and energy metabolism, which further proved the important role of FABP4 in energy metabolism of colon cancer." (PMID 33088219, 2020). "Therefore, further research into the role of FABP4 in colon cancer is needed." (PMID 35479956, 2022). "In summary, FABP4 could promote colon cancer metastasis by inducing EMT." (PMID 33088219, 2020). "The results above confirmed that FABP4 could promote colon cancer metastasis in vivo and in vitro." (PMID 33088219, 2020). "Therefore, FABP4 could endow colon cancer cells with mesenchymal properties, characterized by reducing cell-to-cell adhesion regulated by E-cadherin, and increasing the expressions of mesenchymal biomarkers." (PMID 33088219, 2020). "This is consistent with evidence that FABP4 promotes lipid‐induced EMT in other contexts, such as colon cancer." (PMID 41454478, 2026). "The results showed that the expression levels of ACSL6, CYP19A1, LRP2, OSBPL3 and SLCO1A2 were considerably increased, while those of ACOX1, FABP4, PLAAT5, PPARGC1A and TNFAIP8L3 were decreased in colon cancer." (PMID 38045683, 2023). "Secondly, we studied the expression and pathophysiological significance of CYP19A1 in vitro and in vivo, and further studies are needed on other LMGs including FABP4, LRP2, SLCO1A2, PPARGC1A and ALOXE3 in colon cancer." (PMID 37055842, 2023). "Collectively, we screened the six LMGs including CYP19A1, FABP4, LRP2, SLCO1A2, PPARGC1A and ALOXE3, and constructed a signature to predict prognosis and immunotherapeutic response in colon cancer, which was extendedly and externally validated." (PMID 37055842, 2023). "Here we integrated CYP19A1, FABP4, LRP2, SLCO1A2, PPARGC1A and ALOXE3 with clinicopathological information of patients to construct a prognostic nomogram in colon cancer." (PMID 37055842, 2023). "The purpose of this study is to determine the effects of fatty acid binding protein 4 (FABP4), a transporter for lipids, on colon cancer progression." (PMID 33088219, 2020). "Experimental studies have shown that the FABP‐4 inhibitor BMS309403 could suppress the invasion and migration of colon cancer cells." (PMID 40857027, 2026). "To explore the roles of FABP4, CDR2L, and FSTL3 in cellular composition and molecular profiles, we analyzed single-cell RNA-sequencing (scRNA-seq) data from 49,589 cells derived from 23 colon cancer samples (GSE200997)." (PMID 40595026, 2025). "In conclusion, FABP4, CDR2L, and FSTL3 can be used as prognostic markers for colon cancer." (PMID 40595026, 2025). "FABP4 enhances the EMT process of colon and cervical cancer cells through the AKT pathway and promotes the migration, invasion, and cytoskeleton reorganization of colon cancer and cervical cancer cells, indicating that FABP4 promotes metastasis." (PMID 36532833, 2022). "In this study, we found a close relationship between tumor immunity and FABP4 expression in COAD patients, which may be a useful biomarker for the immunotherapy of colon cancer." (PMID 36264920, 2022). "Our study showed the migration and invasion of colon cancer cells were significantly enhanced when co-cultured with extract of adipose tissues or overexpressed FABP4, but the proliferation did not change." (PMID 33088219, 2020). "According to these results, we speculated that FABP4 may enhance the metabolism and EMT in colon cancer cells partly by activating AKT pathway." (PMID 33088219, 2020). "Overall, these results demonstrated that FABP4 enhanced the invasion and migration, but did not change the proliferation of colon cancer cells." (PMID 33088219, 2020).
colon cancer (continued). "FABP4 overexpression could increase FAs transport to enhance energy and lipid metabolism, and activate AKT pathway and EMT to promote the migration and invasion of colon cancer cells." (PMID 33088219, 2020). "To investigate the effects of adipose tissues and FABP4 on colon cancer cells invasion and migration, we incubated the human colon cancer cell lines HCT-8 and HCT-116 with extract of adipose tissues with or without specific FABP4 inhibitor BMS309403." (PMID 33088219, 2020).
heart failure (28 papers, 2013 to 2025). Inability of the heart to pump blood at an adequate rate to meet tissue metabolic requirements. "Previous studies have linked elevated FABP-4 levels to LV hypertrophy, heart failure, and both systolic and diastolic dysfunction." (PMID 39711764, 2024). "Recent studies reported that FABP4 mRNA expression is higher in heart failure patients than in normal patients and is linked with heart failure severity." (PMID 36311201, 2022). "Elevated FABP4 levels have been linked to a modestly higher risk of heart failure, and sudden cardiac death, and a variant near FABP4 was proposed to reduce the risk of cardiovascular incidents and increase plaque stability." (PMID 30002403, 2018). "Our group has reported a positive association between FABP4 and incident heart failure in this cohort." (PMID 24455402, 2013). "FABP4 also showed a strong association between aortic artery stiffness and heart failure." (PMID 38731797, 2024). "FABP3: fatty acid binding protein 3; FABP4: fatty acid binding protein 4; HF: heart failure; NYHA: New York heart association; LVEF: left ventricular ejection fraction; NTproBNP: pro-B-type natriuretic peptide; eGFR estimated glomerular filtration rate (CKD-EPI equation)." (PMID 36978893, 2023). "Furthermore, a large-scale prospective study showed that concentration of FABP4 predicted the risk of heart failure during a median follow-up of 10.7 years." (PMID 25142635, 2014). "Taken together, CD34+ cells can accelerate the accumulation of lipids in the heart by differentiating into FABP4+ fibroblasts, resulting in lipid toxicity, which leads to the progression of heart failure." (PMID 39198543, 2024). "In contrast, CD34+ cells can accelerate the accumulation of lipids in the heart by differentiating into FABP4+ fibroblasts, resulting in lipid toxicity that leads to the progression of heart failure." (PMID 39198543, 2024). "Researchers found that individuals with cardiac fibrosis had higher FABP4 levels in their ventricular tissue and serum and that FABP4 levels were related to cardiac dysfunction and heart failure biomarker levels." (PMID 36311201, 2022). "Rodríguez-Calvo R, Girona J, Alegret JM, Bosquet A, Ibarretxe D, Masana L. Role of the fatty acid-binding protein 4 in heart failure and cardiovascular disease." (PMID 32236321, 2020). "We have recently reported that mice doubly deficient for fatty acid binding protein 4 (FABP4) and FABP5 (FABP4/5DKO) develop heart failure under pressure overload by TAC30." (PMID 30104639, 2018). "Up-regulation of FABP4 expression and other adipokines in heart failure has been demonstrated in recent studies, indicating complex neurohormonal and metabolic abnormalities associated with heart failure." (PMID 25142635, 2014). "Accumulating evidence of a causative role of FABP4 in cardiac dysfunction would prove that FABP4 is a novel target for prevention of heart failure." (PMID 25142635, 2014). "We have explored the relationship between FABP4 and the N-terminal fragment of pro-B-type natriuretic peptide (NT-proBNP) as a clinical parameter of heart failure (HF)." (PMID 23642261, 2013). "FABP4 levels were higher in heart failure patients compared to patients without heart failure and correlated with heart failure severity and NT-proBNP levels, and FABP4 is associated with incidence of heart failure." (PMID 32727561, 2020). "Interestingly, studies have identified FABP4 as a novel adipokine, and serum concentrations have been directly related to heart failure and CVD43,44." (PMID 31792287, 2019). "These proteins either act as positive regulators of cell death (HBG1, HBB, HBD, and HBA1) or are involved in the cellular response to tumor necrosis factor (FABP4, GPD1, THBS1, ASS1, and PCK2), suggesting that apoptosis may be an important cause of heart failure in patients with COVID-19." (PMID 38087340, 2023).
heart failure (continued). "Fatty acid-binding protein 4 (FABP4) is a lipid-binding protein that can regulate glucose and lipid homeostasis, and its expression was elevated in heart failure." (PMID 36311201, 2022). "Moreover, in a mouse model of heart failure, the depletion of CD34+ cells resulted in a reduction in FABP4+ fibroblasts, triglyceride (TG) content, and myocardial fibrosis and an improvement in cardiac function." (PMID 39198543, 2024). "In addition, immunofluorescence staining demonstrated elevated expression levels of fibroblast markers (such as POSTN and PDGFRA) and FABP4+ fibroblasts (FABP4 + POSTN+ and FABP4 + PDGFRA+) in the heart failure group compared to those in the control group." (PMID 39198543, 2024).
colorectal cancer (27 papers, 2019 to 2026). A primary or metastatic malignant neoplasm that affects the colon or rectum. "Previous studies have shown that the expression of FABP4 is significantly associated with advanced tumor staging, poorer disease-free survival, and overall survival in colorectal cancer, consistent with our findings." (PMID 39399504, 2024). "Another study showed that serum FABP4 levels increased in patients with colorectal cancer in China compared with normal test subjects, indicating that FABP4 is a risk factor and a potential biomarker." (PMID 36114448, 2022). "Moreover, patients with elevated circulating FABP4 levels indicates higher risk of colorectal cancer." (PMID 35899119, 2022). "FABP4, an intracellular lipid chaperone, is downregulated in TC and colorectal cancer, correlating with cancer cell proliferation, invasion, and patient prognosis." (PMID 40119647, 2025). "Subsequently, it has been reported that FABP4 depletion suppresses the activation of stemness properties in colorectal cancer via modulation of the ERK/mTOR pathway." (PMID 41392988, 2025). "In colorectal cancer, the expression of FABP4 was significantly increased in the high CEA group (>5 ng/ml) compared with the low CEA group (<=5 ng/ml)." (PMID 36532833, 2022). "In our study, it was also found that gastric and colorectal cancers with high FABP4 expression had a worse prognosis." (PMID 36532833, 2022). "Among patients with colorectal cancer, circulating FABP4 is higher than the levels in the control groups before surgery, and remarkedly reduces after operation." (PMID 35899119, 2022). "In colorectal cancer, high expression of FABP4 has been found to be closely related to tumor recurrence." (PMID 36338624, 2022). "We analyzed the different clinicopathological features of FABP4 expression in patients with gastric and colorectal cancer." (PMID 36532833, 2022). "Decreased expression of FABP4 was detected in colorectal cancer patients and colorectal cancer cells." (PMID 36532833, 2022). "In this regard, FABP4 was previously found to be a potential biomarker for the diagnosis of colorectal cancer in Chinese patients." (PMID 36532833, 2022). "It was found that in gastric cancer and colorectal cancer, FABP4 was correlated with overall survival and progression-free survival, and it was also correlated with overall survival in LIHC, BRCA, and THCA." (PMID 36532833, 2022). "Dongmei Zhao showed that miRNA-211 enhances the ability of colorectal cancer cells to invade and migrate by targeting FABP4 via PPARγ." (PMID 34422636, 2021). "These included PRSS2, EPHB6 and FABP4, which showed correlation with colorectal cancer prognosis, whereas high expression of these genes was related to poor prognosis." (PMID 32033604, 2020). "In colorectal cancer, FABP4 was found to be downregulated and its upregulation inhibited the migration, invasion, and proliferation of cancer cells." (PMID 31803141, 2019). "In previous studies, we demonstrated upregulation of FABP4 and CD36 in SARFIFA-positive gastric and colorectal cancers by investigating spatial and bulk RNA-data as well as immunohistochemical protein expression." (PMID 38216952, 2024). "Recent studies have been shown that FABP4 overexpression promotes epithelial-mesenchymal transition (EMT) and tumor cell metastasis by increasing the FFAs content into colorectal cancer cells co-cultured with adipocytes." (PMID 37760840, 2023). "FABP4 differentially expressed gene analysis in gastric and colorectal cancer was performed using R DESeq2 through the TCGA database, and GSEA was used to identify FABP4 correlated signaling pathways." (PMID 36532833, 2022). "Among them, MMP12 was highly expressed in colorectal cancer tissues, while ARMCX2, CEBPA, CXCL13, FABP4, HOXC6, SIGLEC1 and VSIG4 were more expressed in normal tissues than in cancer tissues." (PMID 36544770, 2022). "In colorectal cancer, miR-211 inhibits cell migration, invasion, and EMT process by targeting FABP4." (PMID 35899119, 2022).
colorectal cancer (continued). "Colorectal cancer (CRC) represents another tumor in which adipocytes are an integral part of the tumor micro-environment, therefore circulating FABP-4 may play a role in CRC development by providing a fatty acid supply for tumor growth." (PMID 37833736, 2023). "The colorectal cancer cells also use FABP4 and FABP5, rather than CD36, to scavenge extracellular FFAs and intracellular lipids, in contrast to other cancers, such as melanoma or ovarian and prostate carcinomas." (PMID 37760840, 2023).
endothelial dysfunction (26 papers, 2011 to 2025). In vascular diseases, endothelial dysfunction is a systemic pathological state of the endothelium (the inner lining of blood vessels) and can be broadly defined as an imbalance between vasodilating and vasoconstricting substances produced by (or acting on) the endothelium. "In diabetic subjects, elevated FABP4 levels in the serum have been associated with endothelial dysfunction." (PMID 23642261, 2013). "We have previously reported that plasma FABP4 levels are associated with endothelial dysfunction in diabetic patients." (PMID 22709426, 2012). "Chronic administration of BMS309403, a small molecule FABP4 inhibitor, significantly improved endothelial dysfunction in ApoE-deficient mice." (PMID 22121495, 2011). "Our results supports that FABP4 plays a direct causal role in endothelial dysfunction and could be a good therapeutic target for patients with T2D." (PMID 22709426, 2012). "In addition, we recently demonstrated that high levels of plasma FABP4, as other inflammation mediators, were associated with endothelial dysfunction assessed by peripheral artery tonometry." (PMID 22709426, 2012). "High levels of fatty acid-binding protein 4 (FAPB4) in atherosclerotic plaques have been associated with increased local inflammation, endothelial dysfunction, and plaque vulnerability." (PMID 35955575, 2022). "FABP4 is also thought to be involved in neointimal hyperplasia after vascular injury through endothelial dysfunction and proinflammatory cytokine production." (PMID 36142365, 2022). "Most importantly, we determined that FABP4 can lead to endothelial dysfunction by ERK/JNK/STAT-1 signaling, eNOS, and SDF-1 pathways." (PMID 33287461, 2020). "Overall, FABP4 can lead to endothelial dysfunction through different mechanisms, including ERK/ JNK/ STAT-1, eNOS, and SDF-1 signaling pathways." (PMID 33287461, 2020). "In vitro studies have shown that FABP4 contributes to endothelial dysfunction and exhibits a cardiomyocyte depressing action." (PMID 23642261, 2013). "In this study, FABP4 could enhance endothelial adhesion and induce endothelial dysfunction by activating ERK/JNK/STAT-1 signaling pathways and inhibiting both eNOS and SDF-1 expression in HCAECs." (PMID 33287461, 2020). "Interestingly, previous in vitro studies showed that FABP4 can inhibit the insulin and endothelial nitric oxide synthase (eNOS)-signaling pathways and can lead to endothelial dysfunction in human umbilical vein endothelial cells (HUVECs)." (PMID 33287461, 2020). "Furthermore, FABP4 promotes endothelial dysfunction by decreasing the activation of nitric oxide synthase in vascular endothelial cells." (PMID 32856199, 2020). "Emerging data suggests an essential involvement of FABP4 in endothelial dysfunction." (PMID 30857223, 2019). "Interestingly, a study showed that FABP4 expression decreased phosphorylation of eNOS and NO production in microvascular endothelial cells, contributing to endothelial dysfunction." (PMID 25506691, 2014). "This study examined the effects of fatty acid binding protein 4 (FABP4), an adipokine that is associated with cardiovascular risk, endothelial dysfunction and proinflammatory effects, on the migration and proliferation of human coronary artery smooth muscle cells (HCASMCs)." (PMID 24312381, 2013). "Thus, in the cluster of malignant, we speculated that the high expression of Cd36, Lpl, Gpihbp1, Fabp4, and Pparg was important in the metabolism of FAs and may contribute to endothelial dysfunction." (PMID 40440080, 2025). "Therefore, we examined the effect of OXA on endothelial cells and found no detectable impact on genes associated with endothelial dysfunction and vascular injury, including Fabp4, Pcdh17, Esm1, and Cd34." (PMID 37697332, 2023).
endothelial dysfunction (continued). "Moreover, FABP4 inhibits the activation of the insulin-signaling pathway, resulting in decreased activation of the endothelial nitric oxide synthase (eNOS) in vascular endothelial cells and nitric oxide production, inducing endothelial dysfunction." (PMID 30857223, 2019). "Disruption of PPARγ signaling can lead to altered expression of genes involved in lipid metabolism, such as fatty acid binding protein 4 (FABP4) and CD36, contributing to the development of a pro-inflammatory state and endothelial dysfunction." (PMID 39062815, 2024).